UNC119B (unc-119 lipid binding chaperone B)
Description:
Myristoyl-binding protein that acts as a cargo adapter: specifically binds the myristoyl moiety of a subset of N-terminally myristoylated proteins and is required for their localization. Binds myristoylated NPHP3 and plays a key role in localization of NPHP3 to the primary cilium membrane. Does not bind all myristoylated proteins. Probably plays a role in trafficking proteins in photoreceptor cells.
Synonyms: MGC5139; POC7B
Tractability: Small molecule: a structure with a bound ligand is known. PROTAC: ubiquitination databases record sites on it; its protein half-life has been measured.
Gene: Protein-coding gene on chromosome 12 (120,710,440 to 120,723,640, forward strand). Ensembl gene ENSG00000175970.
Subcellular location: Cell projection, cilium
Subcellular location (Human Protein Atlas): Annulus; Cytokinetic bridge; Cytosol; Flagellar centriole; Mitotic spindle; End piece; Mid piece; Principal piece
Pathways (Reactome):
Organelle biogenesis and maintenance: Trafficking of myristoylated proteins to the cilium
Gene Ontology:
Molecular function: lipid binding; protein binding
Biological process: cilium assembly; lipoprotein transport; nervous system development
Cellular component: ciliary transition zone; sperm end piece; sperm midpiece; sperm principal piece; cilium; cytosol
Genetic constraint (gnomAD): Loss-of-function variants: 14 observed, 18.68 expected, observed/expected ratio (o/e) 0.75, 90% interval 0.49 to 1.17. The upper end of that interval is the gene's LOEUF score, 1.17, which puts it in group 5 of 6, group 1 being the genes least tolerant of losing a copy. Missense variants: 349 observed, 309.15 expected, observed/expected ratio (o/e) 1.13, 90% interval 1.03 to 1.23. Synonymous variants: 144 observed, 116.24 expected, observed/expected ratio (o/e) 1.24, 90% interval 1.08 to 1.42.
Homologues: Orthologues: chimpanzee UNC119B (100% identical), macaque UNC119B (100% identical), dog UNC119B (96% identical), guinea pig UNC119B (93% identical), mouse Unc119b (90% identical), rat Mlec (84% identical), zebrafish unc119b (68% identical), pig UNC119B (56% identical), Drosophila melanogaster unc-119 (53% identical), Caenorhabditis elegans unc-119 (49% identical). Paralogues in human: UNC119 (54% identical).
Diseases named in the same sentence as UNC119B in open-access papers:
UNC119B is named in the same sentence as 6 diseases in open-access papers, as found by Europe PMC text mining. Sharing a sentence is not in itself a finding about the gene and the disease. The quoted sentences say what the papers report.
ciliopathy (1 paper, 2021). A genetic disorder of the cellular cilia or the cilia anchoring structures, the basal bodies, or of ciliary function. "Further experiments inducing full loss of arl13b or unc119b function in a cep290-deficient larvae may show more severe ciliopathy phenotypes." (PMID 34155518, 2021).
cardiovascular diseases (1 paper, 2024). "However, the roles of UNC119B, RERE, and FNDC3B in cardiovascular diseases are not known." (PMID 38303056, 2024).
tumor (1 paper, 2023). "On the other hand, UNC119B could inhibit the function of immune cells associated with tumor suppression and IFN response, leading to immune escape and immunotherapy resistance." (PMID 37903971, 2023). "UNC119B was identified to play a carcinogenic role in tumor proliferation, pathological grade and stage, suggesting that UNC119B showed promise to be a crucial therapeutic target against HCC." (PMID 37903971, 2023). "High expression of OSBP2 and UNC119B was related to advanced tumor stage of HCC." (PMID 37903971, 2023). "To verify the role of NR6A1, OSBP2 and UNC119B in HCC progression, we analyzed the correlation between gene expression and HCC tumor size, pathological grade and clinical stage according to TCGA database." (PMID 37903971, 2023).
UNC119B also shares sentences with these, for which no sentence is quoted: hepatocellular carcinoma (1 paper); Joubert syndrome (1); liver cancer (1).